TCP1 (t-complex 1)
Diseases named in the same sentence as TCP1 in open-access papers (continued):
Sharing a sentence is not in itself a finding about the gene and the disease.
tumor (continued). "In addition to inducing tumor apoptosis, TCP-1/TNFα or TCP-1/IFNγ also increased the infiltration of CD8+ and CD4+ T cell in the tumor leading to enhanced antitumor immunity." (PMID 27342639, 2016). "Although no direct association with cancer metastasis has been found, these proteins have close relationships with gene expression, cell signal transduction and the cell cycle; therefore, TCP-1 affecting the synthesis of these proteins is likely to influence tumor metastasis." (PMID 26556873, 2015). "TCP1 forms with seven other subunits a TRiC complex that functions as a chaperone protein, and targeting TCP1 may suppress the proliferation and survival of tumour cells." (PMID 39174525, 2024). "Therefore, TCP-1 subunits identified in the present study may act as TAAs required for capable of activating tumor-specific immunity." (PMID 29360750, 2018). "Some genes in the overall sample group could be related to tumor progression in association with patient survival; only NOS1, TCP1, and DKFZp564N2472 had higher expression levels in patients with lower survival, while the remaining genes had lower expression levels in these patients." (PMID 29285214, 2017). "It was shown that down-regulated TCP-1 could reduce the metastasis of the tumor greatly." (PMID 26556873, 2015). "This correlation suggests a pivotal role for TCP1 in the modulation of AML cell and tumor growth, particularly through its influence on proliferation signaling pathways." (PMID 40430849, 2025). "In this review, we summarize the basic structure and function of chaperonin containing TCP-1 complex and CCT3, and discuss the role of CCT3 in tumor development." (PMID 39928781, 2025). "CCT1, also known as tailless complex polypeptide 1 (TCP1), belongs to the CCT α subunit and plays a role in tumour proliferation and survival." (PMID 39174525, 2024). "Among these proteins, tailless complex polypeptide 1 (TCP1), a subunit of chaperonin-containing T-complex protein-1 (CCT), plays a role in tumour proliferation and survival." (PMID 39174525, 2024). "The mRNA expression levels of TCP1, CCT2/3/4/5/6A/7/8 in HCC patients were lower in grade 1/2 than grade 3/4, while CCT6B expression decreased as the tumor grade increased." (PMID 34676169, 2021). "Compared with the unconjugated TNFα and IFNγ, the conjugated groups through TCP-1 further increased the infiltration of both CD8+ and CD4+ T cell in the tumor." (PMID 27342639, 2016). "Although their downregulation was confirmed in additional in vitro experiments, only TCP1 could be confirmed in patients, i.e. TCP1-low-expressing tumors showed also low-levels of SAMHD1 expression by qRT-PCR on tumor biopsies." (PMID 37667113, 2024). "The results of functional analysis, in vitro experiments and clinical cohort studies suggested a tumor‐suppressive role of WDR37, and the mechanism may be related to the role of TCP1 complex." (PMID 38304253, 2023). "Interestingly, TCP1 was overexpressed in EOC samples, especially in higher tumor grade and higher FIGO stage samples." (PMID 34162426, 2021). "We here chose 1 μg/mouse for TNFα which could partly inhibit tumor growth and avoid masking the action of combined treatment of TCP-1/TNFα and TCP-1/IFNγ." (PMID 27342639, 2016). "Taken together, the data suggest that TCP-1/TNFα and TCP-1/IFNγ could increase the generation of T lymphocyte in the spleen and enhance the penetration of T lymphocytes into the tumor." (PMID 27342639, 2016). "To further determine whether the upregulation of CCT4 in tumor cells reflects a global activation of the TRiC complex or exhibits subunit-specific expression patterns, we systematically analyzed the expression profiles of all eight CCT family subunits (TCP1, CCT2–CCT8) at the single-cell level." (PMID 41403933, 2025).
tumor (continued). "Data showed that TCP-1/IFNγ could colocalize with tumor vasculature, but not with blood vessels in normal organs including brain, heart and normal colon tissues, indicating that IFNγ protein did not negatively affect the binding ability of TCP-1 to tumor vasculature." (PMID 27342639, 2016).
cancer (20 papers, 2008 to 2025). A tumor composed of atypical neoplastic, often pleomorphic cells that invade other tissues. "Although molecular mechanisms underlying TCP1 role in promoting cancer are unknown, our data point towards SAMHD1 as a key factor, confirming the prognostic value of SAMHD1 through the modulation of TCP1 levels, which may putatively also affect IL signaling." (PMID 37667113, 2024). "TCP1 is an oncogene in various cancers, which improves cell proliferation through the activation of the PI3K/AKT/mTOR signaling pathway." (PMID 37416927, 2023). "Another group of chaperone genes, such as CCT6A, CCT4, TCP1, CCT5, PTGES3 and CCT7, were previously implicated in cancer cell proliferation and predicts poor prognosis in HCC36,37." (PMID 33431814, 2021). "Cell proliferation assay using MTT and colony formation assays were performed to uncover the role of TCP1 in cancer cell growth." (PMID 34162426, 2021). "Second, studies have shown TCP-1 can influence the synthesis of cell-cycle proteins, such as cyclin E, which has been reported to be highly expressed in many types of cancer cells and to regulate the cell cycle." (PMID 26556873, 2015). "Genes encoding for proteins TPRKB, T-Complex 1 (TCP1), Olftactomedin 1 (OLFM1), LDOC1 and HTRA3 have been implicated positive or negatively in cancer progression." (PMID 18793431, 2008). "Activation of the PI3K signaling pathway may contribute to the process of TCP1 upregulation in promoting cancer progression." (PMID 37818090, 2023). "The mechanism of cancer progression promoted by TCP1 upregulation may be linked to the activation of the PI3K signaling pathway, and TCP1 may serve as a novel target for the treatment of OC." (PMID 34162426, 2021). "On the one hand, the expression levels of CNV and mRNA were positively correlated in most cancer types, especially in TCP1; on the other hand, the level of CCG methylation was negatively correlated with the level of mRNA expression in most cancers." (PMID 41312091, 2025). "Significant upregulation of TCP1, CCT2/3/5/6A/8 levels have been found in a variety of cancers, with CCT3/6A/8 the best studied in HCC, while there are few studies on CCT4/5/7." (PMID 34676169, 2021). "Based on the Oncomine database, we found that mRNA expressions of TCP1, CCT2, CCT6A, CCT7, STIP1 and HSP90AB1 were significantly upregulated in cancerous samples compared with normal samples in various types of cancer, including BC." (PMID 32194784, 2020). "T complex polypeptide 1 (TCP-1) which acts as a member of the chaperonin assists the synthesis of cytoskeletal proteins, so far it has approved that TCP-1 is over-expressed in varieties of cancers and shows increased expression with advancing stage." (PMID 26556873, 2015). "Therefore, inhibition of TCP1 occurred via decrease of p-AKT in the PI3K/AKT/mTOR pathway to inhibit the development of OC, which was a central regulator of metabolism, survival, and proliferation in normal and cancer tissues." (PMID 34162426, 2021).
infection (4 papers, 2010 to 2025). The state of being infected such as from the introduction of a foreign agent such as serum, vaccine, antigenic substance or organism. "Interestingly, discrimination analysis identified a number of T cell-related genes (e.g., IL7R, LY9, and TCP1) that were uniquely upregulated with Makona-C07 infection, which may reflect aberrant T cell activation associated with fatal outcomes in EVD patients." (PMID 34484156, 2021). "After infection, knockdown of TCP1 protein expression in A2780 cells was confirmed by Western blotting." (PMID 34162426, 2021).
TCP1 also shares sentences with these, for which no sentence is quoted: glioblastoma (2 papers); lung adenocarcinoma (2); prostate carcinoma (2); acute tubular necrosis (1); adenocarcinoma (1); Allergy (1); Behçet’s disease (1); blastoma (1); brain malformations (1); Chagas disease (1); Chronic colitis (1); co-infection (1); colonic carcinoma (1); diffuse large B-cell lymphoma (1); esophageal cancer (1); fibrosarcoma (1); Intellectual disability (1); Lewis body disease (1); lung carcinoma (1); malnutrition (1); mitochondrial disease (1); neurodegenerative disease (1); neurological disorders (1); neuropathies (1); non-small cell lung carcinoma (1); Parkinson disease (1); protein misfolding diseases (1); renal cell cancer (1); renal failure (1); retinal degeneration (1).
A further 7 diseases each share a sentence with TCP1 in 1 paper.